DUOX2 (dual oxidase 2)
Diseases named in the same sentence as DUOX2 in open-access papers (continued):
Sharing a sentence is not in itself a finding about the gene and the disease.
colorectal cancer (13 papers, 2015 to 2025). A primary or metastatic malignant neoplasm that affects the colon or rectum. "An integrative analysis identified colorectal cancer-related genes, including LCN2 and DUOX2, for which gene expression is correlated with the abundance of colorectal cancer-associated bacteria, such as Ruminococcaceae and Veillonella." (PMID 31992345, 2020). "Both Duox2 and DuoxA2 exhibit overexpression in human pancreatic and colorectal cancer cells, thereby increasing the susceptibility of these cells to tumor progression via the generation of elevated levels of reactive oxygen species (ROS) that promote tumor progression." (PMID 40909948, 2025). "In addition to its role in the persistent and recurrent inflammatory of UC, the DUOXA2/DUOX2 pathway is also involved in the development of UC-associated adenomas and colorectal cancer." (PMID 32190668, 2020). "In pancreatic and colorectal cancer cells, the expression of Duox2 is regulated by the transcription factor STAT1." (PMID 40909948, 2025). "In colorectal cancer cells, knockdown of DUOX2 inhibits invasion and migration that can be reversed by the overexpression of RPL3." (PMID 38925865, 2024). "DUOXA2 was maturation factor of an oxidative protein DUOX2, which promotes invasion and metastasis of colorectal cancer." (PMID 36930369, 2023). "However, a previous study showed that DUOX2 knockdown decreases the migration and invasion of colorectal cancer cells in vitro." (PMID 37891879, 2023). "Also, DUOX2 protein level in stages II–IV of colorectal cancer was significantly higher than that in stage I." (PMID 26839536, 2016). "Expression levels of both DUOX2 and DUOXA2 have been reported to be up-regulated in association with iUC, and in UC-associated colorectal dysplasia and colorectal cancer and are involved specifically in inflammation and regulated on a crypt-by-crypt basis in UC." (PMID 25991924, 2015). "Moreover, RPL3 interacts with DUOX2 that promotes the progression of colorectal cancer cells." (PMID 38925865, 2024). "Moreover, the level of DUOX2 protein in tissues of CRC was closely related to clinical tumor stage, indicating that DUOX2 protein could promote tumor metastasis and be used as a predictor for the development and progression of colorectal cancer." (PMID 26839536, 2016).
goiter (13 papers, 2016 to 2025). Enlargement of the thyroid gland usually caused by lack of iodine in the diet, hyperthyroidism, or thyroid nodules. "In the biallelic group, we found that 81.8% (18/22) of cases (16 cases of GIS, 4 cases of goiter, and 2 cases of TD) harbored variants in DUOX2, two GIS cases had DUOXA2 variants, and two TD cases had TSHR variants." (PMID 34539567, 2021). "The second case harbored a novel, maternally inherited variant, DUOX2 p.D1440N, associated with goiter, mildly elevated blood spot and serum TSH (14.8 and 21 mU/L, respectively), and normal FT4 1.39 ng/dL." (PMID 32765423, 2020). "Biallelic DUOX2 mutations explaining the DH were detected in a single patient (#4), who had a goiter and a positive perchlorate discharge test." (PMID 33692749, 2020). "The aim of this study was to screen DUOX2 mutations in 10 unrelated Chinese children with CH and goiter by standard polymerase chain reaction (PCR)-based sequencing and clarify genotype–phenotype relationships." (PMID 29435108, 2018). "In conclusion, we have identified two missense DUOX2 mutations in Chinese patients with CH and goiter." (PMID 29435108, 2018). "A greater proportion of patients in the “DUOX2 monoallelic variant” group had normal thyroid morphology (50.00%, 10/20), whereas a greater proportion of patients in the “DUOX2 biallelic variant” group had goiter (59.57%, 28/47)." (PMID 41334443, 2025). "However, a significant association was found between DUOX2 biallelic variants and goiter, with monoallelic DUOX2 variants often associated with normal thyroid morphology." (PMID 41334443, 2025). "Previous studies have applied next-generation sequencing (NGS) as a cost-efficient and powerful approach and confirmed that the conventional goiter-associated candidate genes DUOX2 and TPO may be related to TD, suggesting that the genotype-phenotype relationship of CH is increasingly complex." (PMID 32425884, 2020). "In contrast to Patient #4, who presented with oligogenic variants of DUOX2, THRB, and TPO and underwent continuous follow-up owing to a simple goiter, Patient #15 had an enlarged nodular goiter and was finally diagnosed with thyroid follicular adenoma." (PMID 39029043, 2024). "Our analysis identified DUOX2 (MIM #606759) compound heterozygous mutations (ENST00000603300: p.Lys530X, p.Arg1110Gln) were inherited by both sisters from their father and mother respectively, and may be causative to goiter manifestation." (PMID 28222800, 2017). "New thyroid phenotypes have recently been described in known genes, such as thyroid ectopy in patients with DUOX2 variants and gland in situ without goiter or thyroid hypoplasia in patients with PENDRIN, DUOX2 or TPO variants." (PMID 40862110, 2025). "There was also a strong history of goiter (mother and maternal aunt) in F8 but maternal DNA was not available to confirm DUOX2 genotype." (PMID 27525530, 2016). "Furthermore, we also identified a compound heterozygosity involving the DUOX2 gene (ENST00000603300:c.1588A > T:p.Lys530* and c.3329G > A:p.Arg1110Gln) in both sisters which are inherited from both parents and may be correlated with early onset of goiter." (PMID 28222800, 2017).
colon cancer (11 papers, 2013 to 2025). "In 5-fluorouracil-resistant colon cancer cells, it was shown that demethylation of DUOX2 gene promoter, encoding dual oxidase 2, is associated with promotion of epithelial-mesenchymal transition and increased oxidative stress." (PMID 40724830, 2025). "On the other hand, in colon cancer, DUOX2 has been observed to increase ROS production due to elevated DUOX2 protein levels, which, in turn, promotes the expression of EMT-associated markers." (PMID 39696702, 2024). "Overexpression of DUOX2/DUOX2A during ulcerative colitis is also thought to be responsible for oxidative DNA damage, which predisposes these patients to colon cancer development." (PMID 31706280, 2019). "Overexpression of Duox in colon cancer is consistent with the upregulation of Duox2 mRNA that has been demonstrated in patients with two pre-cancerous conditions, Crohn’s disease and ulcerative colitis." (PMID 23404210, 2013). "Moreover, we showed that GM influences the contribution of DUOX2 depletion to colon tumorigenesis in an inflammatory model of colon cancer." (PMID 38659246, 2024). "In addition, the tumors from patients with DUOX2 wild-type colon cancer served as a positive control." (PMID 33628596, 2021). "DUOX2, which promoted 5-fluorouracil-induced epithelial-mesenchymal transition by producing reactive oxygen species, appeared to play a significant role in colon cancer chemoresistance and the aggressiveness of this cancer." (PMID 34631510, 2021). "5-FU–resistant SNUC5 colon cancer cellshad higher levels of EMT markers, as well as higher DUOX2 mRNA levels andactivity." (PMID 32453337, 2020). "In colon tumor tissue, similar gene expression changes were found for CYR61, RGS1, DUSP1, DUOX2, and SLC6A14, although the log-fold change was generally lower compared to normal tissue." (PMID 25526028, 2014).
ulcerative colitis (9 papers, 2013 to 2025). An inflammatory bowel disease involving the mucosal surface of the large intestine and rectum. "The gene DUOX2 upregulation and their associative enzymes dual oxidase 2 have been found with an expansion of Proteobacteria in the gut microbiota of patients with Crohn’s disease and ulcerative colitis." (PMID 35004340, 2021). "The identified immune biomarkers (CCL18, DUOX2, GREM1, LCN2, and TNC) demonstrated strong diagnostic efficacy and are key immune genes for ulcerative colitis (UC)." (PMID 40584713, 2025). "The expression levels of core immune genes including CCL18, DUOX2, GREM1, LCN2, and TNC in ulcerative colitis models were detected by fluorescence q-PCR." (PMID 40584713, 2025).
thyroid cancer (8 papers, 2013 to 2025). "Furthermore, TG, FOXE1, and DUOX2 were also shown to be associated with thyroid cancer." (PMID 34209805, 2021). "Overexpression of DUOX1 and DUOX2 in thyroid cancers was also reported, however, the results are inconsistent." (PMID 30558263, 2018). "DUOX1 and DUOX2, formerly known as thyroid oxidases, were specifically expressed in thyroid cancers (THCA)." (PMID 28582771, 2017). "DUOX2 is enzymatically active and could increase the production of reactive oxygen species, suggesting the dysregulation of proteins involved in H2O2 metabolism may be the mechanism underlying genetic factors that increase thyroid cancer susceptibility." (PMID 37780622, 2023). "Gene expression of NOX4, DUOX1 and DUOX2 was not increased in kidney and thyroid cancers with high-level apoptosis and energy metabolism (data not shown), implying some other genes acting as the indicators of oxidative stress." (PMID 28582771, 2017).
Crohn disease (7 papers, 2013 to 2026). A gastrointestinal disorder characterized by chronic inflammation involving all layers of the intestinal wall, noncaseating granulomas affecting the intestinal wall and regional lymph nodes, and transmural fibrosis. "In SAM enteropathy and in Crohn's disease there was increased expression of DUOX2, DUOXA2, lipocalin 2, CEACAM 5 and 7, MUC1, SAA 1, 2 and 4, and CXCL5 genes, and these transcripts were further over-expressed in HIV infection." (PMID 31229436, 2019). "Notably, DUOX2 expression was strongly upregulated in intestinal epithelial biopsies from patients with Crohn's disease." (PMID 42235419, 2026). "Duox2, which was upregulated more than 15-fold in the RNA-seq dataset and about 3-fold in the RT-PCR confirmation, is particularly interesting as it is causally implicated in IBD pathogenesis, being mutated in early onset Crohn’s disease." (PMID 35385524, 2022).
thyroid (7 papers, 2015 to 2024). "However, mouse models with biallelic inactivation of DUOX2 or DUOXA2 present a normal developed thyroid gland with only thyroid dyshormonogenesis." (PMID 32425884, 2020). "However, further work will be required to reveal the roles of the truncated DUOX2 transcript in the pathogenesis of thyroid dysfunction, which is essential for modeling thyroid disease in humans." (PMID 30651277, 2019). "Generally, various genetic and molecular studies addressed the issue of congenital hypothyroidism (for example, anomalies of TSHR, SLC26A7, JAG1, DUOX2, and FOXE1 gene) linking the thyroid dyshormonogenesis to thyroid dysgenesis." (PMID 38791947, 2024). "Nicotinamide adenine dinucleotide phosphate (NADPH) oxidases (Dual oxidase 1, Dual oxidase 2, NADPH oxidase 4) are expressed in the human thyroid gland and function as sources of ROS, suggesting that they may play a role in the pathogenesis of thyroid diseases." (PMID 36326389, 2022).
thyroid dysgenesis (7 papers, 2016 to 2025). "In our study, three patients with either monoallelic or biallelic DUOX2 variants exhibited TD, suggesting a potential link between DUOX2 and thyroid dysgenesis in specific cases." (PMID 41334443, 2025). "Previous works showed mutations in genes typically associated with functional defects, including DUOX2, that had been also detected in thyroid dysgenesis, a finding frequently justified by the association with other genetic events in the oligogenic model of CH." (PMID 36071330, 2023).
lung carcinoma (5 papers, 2013 to 2020). "Some reports have shown that Casp3, some claudins and DUOX1 and DUOX2 are regulated by epigenetic mechanisms during maturation of the rat brain, as well as in ovarian cancer cells and lung cancer." (PMID 27895046, 2017). "For example, research has shown that the promoters of DUOX1 and DUOX2 are methylated, which correlates with their downregulation at the protein level in lung cancer." (PMID 27895046, 2017). "Duox2 was expressed in only a limited number of normal tissues, none of which demonstrated strong (3+) expression, compared to the cancers, where 73% of the prostate adenocarcinomas were 3+ in expression, and 24% of breast, colon and lung cancers were 3+." (PMID 23404210, 2013). "Lung cancer also presents decreased expression of DUOX1 and DUOX2 that iscorrelated with hypermethylation of CpG-rich promoter regions of DUOX genes.Moreover, DUOXA1 and DUOXA2 weredown-regulated in lung cancer cells and lung cancer tissues." (PMID 32453337, 2020). "It has been found that in 50% of lung cancers NADPH oxidase DUOX1 and DUOX2 go under epigenetic silencing via hypermethylation of CpG-rich promoter regions." (PMID 31443700, 2019). "Also, DUOX1 and DUOX2, which belong to the NAPDH oxidase family of enzymes, are methylated in human lung cancer." (PMID 27895046, 2017).
adenoma (4 papers, 2020 to 2025). A neoplasm arising from the epithelium. "During functional experiments, we observed that the truncated protein, hDuox2 K530, was overexpressed in the adenoma in a carrier of the DUOX2 nonsense variant, causing abnormal cell proliferation through endoplasmic reticulum (ER) retention." (PMID 33628596, 2021). "IHC staining with an antibody targeting 1–100 amino acids of Duox2 revealed that its expression level in adenoma tissue was significantly higher than that in normal colon mucosa." (PMID 33628596, 2021). "IL-17A induced increase in Duox2 expression in FAP adenoma and carcinoma tissues could also be corroborated at the protein level." (PMID 40280932, 2025). "Bulk RNA sequencing reveals upregulated Reactive oxygen species (ROS)-inducing enzymes DUOX2 and DUOXA2 in FAP adenomas." (PMID 40280932, 2025). "We demonstrated in vitro that IL-17A leads to an increased expression of DUOX2, which corresponds with the elevated DUOX2 expression observed in FAP adenomas." (PMID 40280932, 2025).
chronic granulomatous disease (4 papers, 2016 to 2023). Chronic granulomatous disease (CGD) is a rare primary immunodeficiency, mainly affecting phagocytes, which is characterized by an increased susceptibility to severe and recurrent bacterial and fungal infections, along with the development of granulomas. "DUOX2 is a member of the large reduced nicotinamide adenine dinucleotide phosphate oxidase family of enzymes that are defective in chronic granulomatous disease." (PMID 27373512, 2016).
chronic pancreatitis (4 papers, 2013 to 2021). A chronic inflammatory process causing damage and fibrosis of the pancreatic parenchyma. "It has been reported that high DUOX2 levels contribute to the progression of PC in patients with chronic pancreatitis." (PMID 33748270, 2021). "In view of our previous results demonstrating marked expression of DUOX in patients with chronic pancreatitis, these data suggest that DUOX2 might be involved in the early phases of pancreatic carcinogenesis and cancer progression." (PMID 27637085, 2016).
deafness (4 papers, 2017 to 2023). An inherited or acquired condition characterized by the complete loss of the ability to hear from one or both ears. "In this case study, we postulated that a combination of SLC26A4, GJB2 and SCARB2 heterozygous mutations may be implicated in deafness, whilst DUOX2 compound heterozygous mutations may be contributed towards thyroid dysfunction." (PMID 28222800, 2017). "In summary, we proposed that PDS in this family could be a polygenic disorder which possibly arises from a combination of heterozygous mutations in SLC26A4, GJB2 and SCARB2 which associated with deafness, as well as compound heterozygous DUOX2 mutations which associated with thyroid dysfunction." (PMID 28222800, 2017). "There were 18 genes linked only to Metabolic hearing loss (including four deafness genes: DMD, DUOX2, CELSR1 and ELMO3) and 54 genes linked only to Sensory hearing loss (including four deafness genes: ARHGAP21, LMO7, UBE3B and ADGRV1)." (PMID 38011198, 2023). "PKHD1L1, DUOX2, CELSR1, ELMO3, ARHGAP21, LMO7 and UBE3B are all defined as deafness genes through work on the mouse orthologues." (PMID 37163093, 2023).
asthma (3 papers, 2016 to 2017). "This connection was recently strengthened by a study demonstrating that an iNOS-Dual oxidase-2-thyroid peroxidase metabolome is the basis of nitrogen radicals and subsequent protein nitration in human severe asthma." (PMID 27524861, 2016). "In addition to the role of Duox in asthma, Nox4 was also identified to express along with Duox1 and Duox2 in bronchial biopsy specimens by using microarray." (PMID 29257052, 2017). "DUOX1 was increased in asthma independent of inflammatory phenotype, and DUOX2 was only increased in nonneutrophilic asthma." (PMID 26836936, 2016). "Nox4 and Duox1 were both elevated and Duox2 was elevated in nonneutrophilic asthma." (PMID 29257052, 2017). "Levels of 8-oxo-dG and NOX4 were elevated in patients with neutrophilic vs nonneutrophilic asthma, DUOX1 was elevated in both, and DUOX2 was elevated in nonneutrophilic asthma in vivo." (PMID 26836936, 2016). "Gene array analysis revealed the presence of NOX4 and DUOX1 and DUOX2 expression, but not the other NOX family members, in primary basal epithelial cells from ≥ 3 of the six donors with asthma." (PMID 26836936, 2016). "In contrast to DUOX1, which was increased in asthma independent of inflammatory phenotype, and DUOX2, which was only increased in nonneutrophilic asthma, NOX4 expression was upregulated only in the bronchial epithelium from patients with asthma with neutrophilic inflammation in vivo." (PMID 26836936, 2016).